ENSG00000288841 (novel protein)
Gene: Protein-coding gene on chromosome 9 (131,432,759 to 131,446,473, forward strand). Ensembl gene ENSG00000288841.
Genetic constraint (gnomAD): Loss-of-function variants: 6 observed, 23.39 expected, observed/expected ratio (o/e) 0.26, 90% interval 0.14 to 0.51. Missense variants: 139 observed, 193.5 expected, observed/expected ratio (o/e) 0.72, 90% interval 0.62 to 0.83. Synonymous variants: 71 observed, 72.53 expected, observed/expected ratio (o/e) 0.98, 90% interval 0.81 to 1.19.